PGR (progesterone receptor)
Diseases named in the same sentence as PGR in open-access papers (continued):
Sharing a sentence is not in itself a finding about the gene and the disease.
endometrial cancer (122 papers, 2003 to 2026). Primary or metastatic malignant neoplasm involving the endometrium (mucous membrane that lines the endometrial cavity). "Progesterone receptor signaling plays important roles in endometrial cancer development, and loss of PGR is linked to the development of aggressive endometrial cancer." (PMID 35269532, 2022). "PGR rs1042838 also appeared to be a risk factor for endometrial cancer (allele A increases the risk)." (PMID 35160095, 2022). "Along with estrogen receptor positivity, progesterone receptor positivity in endometrial cancer is classically associated with type I cancers." (PMID 36052252, 2022). "Here, we explored the relationship between PGR transcript levels and endometrial cancer, and found that elevated PGR expression was associated with better prognosis in UCEC patients." (PMID 33782686, 2021). "Estrogen and progesterone receptor expression, for example, is thought to be associated with endometrial cancer prognosis." (PMID 33381462, 2020). "Resistance to P4 treatment due to loss of either progesterone receptor (PGR) itself or its signaling pathways causes significant difficulty in the treatment of advanced and recurrent endometrial cancer." (PMID 29843645, 2018). "Studies have suggested that estrogen receptor (ER) or progesterone receptor (PR) positive are positively associated with endometrial cancer survive." (PMID 27888807, 2017). "It is well documented that the positivity of estrogen receptor (ER) and progesterone receptor (PR) is positively associated with the prognosis of endometrial cancer, including the survival rate and survival time." (PMID 29207611, 2017). "The human PGR gene (progesterone receptor) has the biomedical SNP marker rs10895068 of endometrial cancer in obese women caused by this gene’s overexpression." (PMID 28105927, 2016). "This alternative TSS disrupts the balance between the α and β isoforms of the progesterone receptor encoded by this gene; this aberration doubles the risk of endometrial cancer in overweight women." (PMID 26516624, 2015). "Recently, many studies have investigated the role of the PgR +331G/A polymorphism in the etiology of various types of cancer, i.e., breast, ovary and endometrial cancer." (PMID 23349706, 2013). "To studythe roles of Pten and K-ras in endometrial cancer, we generated Pten ablation andoncogenic K-ras mutation in progesterone receptor positive cells (PRcre/+Ptenf/fK-rasG12D)." (PMID 19884980, 2010). "The protein encoded by PGR, a member of the steroid receptor superfamily, regulates the biological effects of progesterone, and it has been studied as an important marker associated with prognosis and disease progression in endometrial cancer." (PMID 36742386, 2023). "Since PGR is only expressed in about 50% of endometrial cancers, the loss of PGR could lead to an increase in PGRMC1 as suggested for ovarian cancer." (PMID 34885064, 2021). "PGR is reported to be overexpressed in UF samples, and the loss of PGR expression may contribute to the development of endometrial cancer as well as resistance to hormonal therapy." (PMID 32608475, 2020). "Furthermore, loss of progesterone receptor (PR) expression in endometrial cancer has been found to be a risk factor for progressive disease." (PMID 22295114, 2012). "It was also shown to increase progesterone receptor expression and sensitize progestin-resistant endometrial cancer cells to medroxyprogesterone-induced apoptosis." (PMID 39796739, 2025). "In endometrial cancer, SPOP mutations alter estrogen receptor-α stability and enhance BET protein degradation, SPOP also regulates multiple substrates, including SRC-3, progesterone receptor, and c-Myc, to exert tumor-suppressive effects 12, 38-40." (PMID 40657370, 2025). "Progestogen binding to the progesterone receptor (PR) delays DNA and RNA replication and decreases estrogen receptor (ER) expression, which in turn reduces endometrial cancer cell proliferation and promotes cell differentiation." (PMID 39588311, 2024).
endometrial cancer (continued). "A phase II study of anastrozole in recurrent ER-/PgR-positive endometrial cancer (the PARAGON trial) showed a low objective response but a meaningful clinical benefit in 44% of patients." (PMID 36696825, 2023). "Metformin sensitizes endometrial cancer cells even progestin-resistant EC cells to progestin by promoting progesterone receptor, downregulating glyoxalase I expression, downregulating glyoxalase I expression." (PMID 37415671, 2023). "Downregulation of progesterone receptor (PGR) in endometrial carcinoma leads to progestin resistance and is a poor prognostic factor." (PMID 38275587, 2023). "As endometrial carcinomas are hormone-dependent, an immunohistochemical marker for estrogen, the progesterone receptor is commonly used prognostically." (PMID 36751174, 2023). "Progestin is one of the main hormone treatment regimens for early-stage estrogen receptor- and progesterone receptor (PR)-positive endometrial cancer (EC)." (PMID 35388173, 2022). "PGR expression correlates with the response of CAH and EC to progestin therapy, suggesting an important role for PGR in pathologies derived from the endometrial epithelium itself, as would be observed in endometrial cancer." (PMID 35326450, 2022). "ER (estrogen receptor) (12 studies) and PR (progesterone receptor) (9 studies) status were important prognostic factors in breast and endometrial cancers (ER status was also important in colorectal cancer)." (PMID 35444210, 2022). "Knockdown of DHCR24 inhibited the metastatic ability of endometrial cancer cells and upregulated progesterone receptor expression." (PMID 36712880, 2022). "Another phenothiazine, perphenazine, was shown to inhibit growth of progesterone-receptor resistant endometrial cancer." (PMID 33841149, 2021). "al demonstrated that the positive expression of progesterone receptor was related to the rate of complete remission of low-grade endometrial cancer after MPA therapy." (PMID 33606091, 2021). "Compared with CCC, EC had a higher frequency of concurrent endometrial cancer (independent endometrial lesions) and estrogen and progesterone receptor expression(p = 0.000)." (PMID 33941230, 2021). "Progesterone treatment leads to increased Gene 33 expression at both mRNA and protein levels, which corresponds to reduced viability of progesterone receptor-positive human endometrial carcinoma cells." (PMID 34206547, 2021). "We identified the expected strong association of co-expression between PGR and ESR1 (q-value < 2.42 × 10− 53 and odds ratio = 182), which is consistent with previous findings from endometrial cancer cohorts." (PMID 32894083, 2020). "We are unclear why G12D mice did not develop mesenchymal uterine tumors although previous study had shown that mice with Kras G12D driven by PR-Cre (progesterone receptor promoter) developed endometrial carcinoma from the epithelial cells." (PMID 33244099, 2020). "In the context of endometrial cancer, receptLoss correctly identified several well-known nuclear hormone receptors, including ESR1, AR, and PGR, that have previously been shown to have low expression in a subset of endometrial carcinomas." (PMID 32894083, 2020). "First, we selected a total of 258 patients with stable expression of PGR gene as endometrial cancer patients, whose expressions were higher than half of samples." (PMID 31781484, 2019). "PGR coexpression genes within endometrial cancer were identified from cBioPortal which is based on the TCGA database, including 549 endometrial cancer tissues." (PMID 30813939, 2019). "The overexpression of the estrogen receptor (ER) and/or progesterone receptor (PR) in endometrial cancer has been effectively utilized in therapeutic strategies in metastatic disease." (PMID 29464050, 2018). "Recent work has shown a role for the progesterone receptor in down-regulating MYC in endometrial cancers." (PMID 29240775, 2017).
endometrial cancer (continued). "The majority of type 1 (96%) and type 2 (82%) endometrial cancers were estrogen and progesterone receptor positive." (PMID 28000774, 2016). "The expression and involvement of estrogen (ER) and progesterone receptor (PR) is extensively studied in endometrial cancer." (PMID 27384477, 2016). "The estrogen and progesterone receptor (ER/PR) status should be obtained at the time of metastacectomy for endometrial cancer." (PMID 27330821, 2016). "Several reports have demonstrated that treatment with an HDACi restores PGR mRNA and protein expression in endometrial cancer cell lines." (PMID 25229191, 2014). "Significance: Traditional hormonal therapy for women with endometrial cancer can be molecularly enhanced by combining progestins with epigenetic modulators, thereby increasing progesterone receptor expression and significantly improving treatment efficacy." (PMID 25229191, 2014). "In summary, our data indicate that with the application of epigenetic modulators, PGR silencing can be reversed and functional PR expression restored in endometrial cancer cells that have lost hormone responsiveness." (PMID 25229191, 2014). "PGR promoter methylation was assessed in a panel of eight endometrial cancer cell lines using bisulfite sequencing." (PMID 25229191, 2014). "Progesterone mediates its inhibitory effects on the endometrium and endometrial cancer via the progesterone receptor (PR), an intracellular steroid receptor with A and B isoforms." (PMID 22911820, 2012). "The aim of this study was to investigate the expression of c-erbB-2 in endometrial cancer, to study its correlation to established prognostic parameters and estrogen receptor (ER) and progesterone receptor (PR) status." (PMID 20167054, 2010). "In endometrial cancer cells, liraglutide induces an upregulation in progesterone receptor (PGR) mRNA levels, promotes its protein expression, markedly enhances phosphorylated AMPK levels, and downregulates its downstream effector molecule p-P71S6K, ultimately inhibiting cell viability." (PMID 40140925, 2025). "One study found that decreased expression of combined ER/PR (estrogen receptor/progesterone receptor) was associated with a poorer outcome in endometrial cancer patients, but hormone receptor status alone did not significantly improve mortality prediction." (PMID 37152960, 2023). "Multiomics analysis of chromatin immunoprecipitation sequencing (ChIP-seq) and RNA sequencing (RNA-seq) were performed in cell lines derived from endometrial cancer and mammary tumor to screen the differential co-regulatory factors of progesterone receptor (PR)." (PMID 37344459, 2023). "Progesterone’s protective role in endometrial cancer may therefore be mediated through its inhibition of EMT in type I EC tissues that retain the progesterone receptor." (PMID 36052252, 2022). "•A selective progesterone receptor modulator ulipristal acetate, used for the treatment of uterine fibroids and selectively inhibits the proliferation and inflammation of leiomyoma cells decreased cell viability and growth in Ishikawa endometrial cancer cells." (PMID 35036597, 2022). "Lack of progesterone receptor in endometrial cancer is associated with poorer prognostic factors, including high tumor grade, non-endometrioid histology and deep myometrial invasion." (PMID 36052252, 2022). "Progesterone receptor (PGR) gene as another classical ERα target was also found to be significantly associated with DSCAM-AS1 expression in endometrial cancer tissue (rho = 0.46, p = 4.0 × 10−10) but not in normal endometrium or uterine tissues." (PMID 35885035, 2022). "In addition, progesterone promotes Gene 33 expression at both the mRNA and protein levels, which corresponds to reduced viability of progesterone receptor-positive human endometrial carcinoma cells." (PMID 34206547, 2021). "PGR expression has been shown to be a prognostic factor for endometrial cancer." (PMID 29843645, 2018).
endometrial cancer (continued). "FASN also inhibits the expression of HER2 and may function as a potential therapeutic target in estrogen receptor- and progesterone receptor-positive endometrial cancers." (PMID 30237984, 2018). "ER- and/or PgR-positive status is generally associated with better prognosis or survival of endometrial cancer, and hormone-receptor-negative status is considered an indicator of aggressive tumor growth and poor prognosis." (PMID 29907137, 2018). "In individual cases of progesterone receptor-positive endometrial carcinoma FIGO IA G1, tumour removal by hysteroscopy and curettage is possible for fertility preservation, followed by progestin therapy with 250 mg MPA for 6–12 months with follow-up in three-monthly intervals." (PMID 29177593, 2018). "Furthermore, genetically silencing DHCR24 inhibited the metastatic ability of endometrial cancer cells and up-regulated PGR expression, which made cells more sensitive to progestin." (PMID 28112250, 2017). "LBH589 treatment also upregulated PGR mRNA expression in KLE endometrial cancer cells." (PMID 25229191, 2014). "Indeed, progesterone has been used as an adjunctive therapy in chemotherapy-free intervals in estrogen and progesterone receptor-positive endometrial cancer for a long time." (PMID 23554793, 2013). "Poorly differentiated endometrial cancers are more frequently associated with lack of expression of the estrogen and progesterone receptor." (PMID 23785665, 2013). "An alteration in the ratio of the expression of the PgR isoforms precedes changes that may lead to endometrial carcinoma." (PMID 23349706, 2013). "Interestingly, SLC40A1 was positively correlated with PGR and exhibited reduced expression in endometrial cancer tissues than normal endometrium, indicating a potential relationship between SLC40A1 and PGR dysfunction as well as a mechanism of endometrial cancer proliferation." (PMID 30813939, 2019). "Ovarian and endometrial carcinomas may well be ER/PgR positive as well." (PMID 20806071, 2010). "Using cell lines and patient-derived preclinical models of endometrial cancer, we discovered an unexpected interplay between the GLP-1 receptor and progesterone receptor." (PMID 40002193, 2025). "The HPA database provided IHC images of endometrial cancer and normal endometrial tissues, allowing us to confirm the differential expression of CDKN2A, SELENOP, GSN, PGR, and TRPC1 at the protein level." (PMID 41244925, 2025). "A recent study showed that PGR and ESR1 peaks in Ishikawa endometrial cancer cells are mostly in the A (active) compartment (79% and 83%, respectively)." (PMID 35681455, 2022). "In addition, the ability of YTHDC1 to splice transcripts has been demonstrated for a vascular endothelial growth factor (VEGF), breast cancer 1 (BRCA1), and the progesterone receptor (PGR) in endometrial carcinoma, but whether these processes are dependent on m6A modification is still unclear." (PMID 33795663, 2021). "On the other hand, immunohistochemical analysis of PGR and PDIA3 expression showed significant downregulation of these factors in endometrial cancer compared to normal tissues." (PMID 33292199, 2020). "PGR (Progesterone receptor), FOXA1 (Forkhead box protein A1), XBP1 (X-box binding protein 1), and TFF1 (Trefoil factor 1) were reported to involve in the estrogen signal in endometrial cancer." (PMID 33324448, 2020). "In human Ishikawa endometrial cancer cells, MET treatment (60 μM) decreased cell numbers and elicited distinct temporal changes in ESR1, KLF9, PGR, PGR-B, KLF4, DKK1, and other tumor biomarker mRNA levels." (PMID 32046384, 2020).
endometrial cancer (continued). "In the study of endometrial carcinoma tissues, ERK1, ERK2, estrogen receptor, and progesterone receptor (PR) expressions were significantly higher than in the normal control group." (PMID 32083122, 2019). "Expression of PGR (PR-A and PR-B) and ESRs (ESR1 and ESR2) has been reported as prognostic factors for endometrial carcinoma." (PMID 29843645, 2018). "In this regard, a recent study from our laboratories demonstrated the progesterone-dependent co-recruitment of KLF9 and the progesterone receptor to the SLPI promoter, concomitant with induction of this gene's expression, in Ishikawa endometrial cancer cells." (PMID 18783612, 2008). "The inhibition of ERα and the stimulation of progesterone receptor (PGR) expression levels in diabetic and non-diabetic obese women with endometrial cancer resulted in an overall improved and progression-free survival rate." (PMID 37298551, 2023). "This must be demonstrated by further experimentation but the findings that 1) there is an inverse relationship between the expression of PGRMC1 and PGR and 2) PGRMC1 levels increase while PGR levels decrease with the increasing grade of endometrial cancers support this concept." (PMID 34885064, 2021). "Contrary, in progestin-resistant endometrial cancer (EC) cells, SIRT1 knockout (SIRT1-KO) results in the upregulation of progesterone receptor (PR) and FOXO1, as well as the downregulation of sterol regulatory element-binding protein-1 (SREBP-1) that increases sensitivity to progestin therapy." (PMID 34769241, 2021). "Three of these NHRs – progesterone receptor (PGR), estrogen receptor 1 (ESR1), and androgen receptor (AR) – have been previously reported to lose expression in subsets of endometrial carcinomas, which confirms that our approach can capture NHRs known to lose expression in endometrial carcinoma." (PMID 32894083, 2020). "The expression of PGR and ESR1 is strongly correlated with the prognosis of endometrial cancer." (PMID 29843645, 2018). "Fertility preservation is not possible in progesterone receptor-negative endometrial carcinoma FIGO IA G1, or in tumours with higher stages or higher grading." (PMID 29177593, 2018). "In hormone-dependent female cancers such as breast and endometrial cancers, CD171 expression has a negative correlation with ER/PgR expression in both breast and endometrial carcinomas in agreement with previous reports." (PMID 27419370, 2016). "However, it is well established that presence or absence of ERα in endometrial cancers, often in relation to progesterone receptor and Erβ, is related to treatment response and survival." (PMID 23935632, 2013). "The link between estrogen-receptor-alpha (ERα), progesterone receptor (PR), hypoxia-inducible factor 1-alpha (HIF1-α), SLUG, and miR-221 circuit was also investigated in obese and nonobese women diagnosed with endometrial cancer, but further studies are needed in this regard." (PMID 34199293, 2021). "Consistent with the established literature, endometrial cancers that lose both ESR1 and PGR expression (DN, for double negative) have poor 5-year survival compared with cancers that do not lose both ESR1 and PGR (DP, for double positive) (q-value = 1.23 × 10− 6, log-rank test)." (PMID 32894083, 2020).